CWC15 (CWC15 spliceosome associated protein)
Description:
Involved in pre-mRNA splicing as component of the spliceosome. Component of the PRP19-CDC5L complex that forms an integral part of the spliceosome and is required for activating pre-mRNA splicing. As a component of the minor spliceosome, involved in the splicing of U12-type introns in pre-mRNAs (Probable).
Synonyms: C11orf5; HSPC148; Cwf15; AD002; ORF5
Tractability: Small molecule: a structure with a bound ligand is known. PROTAC: its protein half-life has been measured.
Gene: Protein-coding gene on chromosome 11 (94,962,620 to 94,973,611, reverse strand). Ensembl gene ENSG00000150316.
Subcellular location: Nucleus
Subcellular location (Human Protein Atlas): Nuclear speckles; Mitochondria
Pathways (Reactome):
Disease: Dengue Virus-Host Interactions
Metabolism of RNA: mRNA Splicing - Major Pathway
Gene Ontology:
Molecular function: protein binding; RNA binding
Biological process: mRNA splicing, via spliceosome; mRNA cis splicing, via spliceosome
Cellular component: catalytic step 2 spliceosome; nuclear speck; nucleus; post-mRNA release spliceosomal complex; post-spliceosomal complex; Prp19 complex; spliceosomal complex; U12-type catalytic step 2 spliceosome; U2-type catalytic step 1 spliceosome; U2-type catalytic step 2 spliceosome; nucleoplasm
Genetic constraint (gnomAD): Loss-of-function variants: 5 observed, 15.98 expected, observed/expected ratio (o/e) 0.31, 90% interval 0.16 to 0.66. The upper end of that interval is the gene's LOEUF score, 0.66, which puts it in group 2 of 6, group 1 being the genes least tolerant of losing a copy. Missense variants: 151 observed, 206.65 expected, observed/expected ratio (o/e) 0.73, 90% interval 0.64 to 0.84. Synonymous variants: 77 observed, 69.83 expected, observed/expected ratio (o/e) 1.1, 90% interval 0.92 to 1.33.
Homologues: Orthologues: chimpanzee CWC15 (100% identical), dog CWC15 (100% identical), guinea pig CWC15 (100% identical), macaque CWC15 (100% identical), rabbit CWC15 (100% identical), rat Cwc15 (99% identical), mouse Cwc15 (99% identical), rat Cwc15-ps3 (94% identical), tropical clawed frog cwc15 (90% identical), pig CWC15 (85% identical), zebrafish cwc15 (84% identical), Caenorhabditis elegans cwc-15 (62% identical), and 1 more.
Diseases named in the same sentence as CWC15 in open-access papers:
CWC15 is named in the same sentence as 8 diseases in open-access papers, as found by Europe PMC text mining. Sharing a sentence is not in itself a finding about the gene and the disease. The quoted sentences say what the papers report.
breast carcinoma (2 papers, 2024 to 2025). "We found that four interacting proteins of SNRPG are also upregulated in Cluster 1 of basal breast cancer patients with respect to Cluster 2: BUD13, CWC15, and SNRNP70 and ZMAT12, forming a cluster of interacting proteins enriched for the U2-type spliceosomal complex." (PMID 40867231, 2025).
CWC15 also shares sentences with these, for which no sentence is quoted: infection (19 papers); tumor (2); attention deficit-hyperactivity disorder (1); COVID-19 (1); psychiatric disorder (1); syndactyly (1); viral infection (1).